GABRB3 (gamma-aminobutyric acid type A receptor subunit beta3)
Diseases named in the same sentence as GABRB3 in open-access papers (continued):
Sharing a sentence is not in itself a finding about the gene and the disease.
autism (continued). "A recent study reported significantly increased variance of GABRB3 expression in the brain of patients with 15q11-13 duplication compared to control subjects and patients with autism." (PMID 24999380, 2014). "One study showed that the expression of GABRB3 was subject to epigenetic alterations that resulted in monoallelic expression in a subset of autism." (PMID 24999380, 2014). "Gabrb3 knockout mice exhibit deficits in social behavior and constitute a potential mouse model for autism." (PMID 24321478, 2013). "This provides support for the evidence from animal models implicating the role of GABRB3 variation in the atypical sensory sensitivity in autism spectrum conditions." (PMID 22769427, 2012). "The idiopathic autism group showed a significant reduction in GABRB3 transcript compared with controls." (PMID 22152151, 2011). "Idiopathic autism samples exhibited significantly lower GABRB3 and significantly more variable SNRPN levels compared to controls." (PMID 22152151, 2011). "We detected two rare variants rs201602655 (p.Val233Met) and rs201427468 (p.Pro365Ser) in GABRG3 in 2 autistic children and six rare single nucleotide variants (c.−693A>T, c.*417C>T, c.*704A>T, c.*1730G>A, c.*2583C>T, c.*3536T>C) in GABRB3 in 6 of 96 patients affected with autism." (PMID 30108208, 2018). "Moreover, our study demonstrated that rs4906902 in GABRB3 and rs4906771 in ATP10A were significantly associated with autism under the recessive model, although these positive results were not replicated in ASD subset of PGC." (PMID 30108208, 2018). "Molecular changes may also influence the expression of genes involved in autism symptoms and genetic syndromes such as GABRB3, FMR1, TSC1 and TSC2." (PMID 29340132, 2018). "Additionally, rs4906902 in GABRB3 and rs4906771 in ATP10A exhibited significant association with autism under the recessive model." (PMID 30108208, 2018). "Other significant risk alleles reported in Caucasians, such as rs7180158, rs7165604, rs12593579 and rs9806546 in GABRB3, did not exhibit a positive association with autism in our samples." (PMID 30108208, 2018). "Similarly, Nurmi and colleagues reported improved linkage of GABRB3 with autism in subset families based on savant skills." (PMID 24999380, 2014). "GABRB3 is a well-characterised candidate gene for autism spectrum conditions." (PMID 22769427, 2012). "Moreover, GABRB3 and ATP10A located on chromosome 15q11-q13 might increase risk for autism in Chinese Han population." (PMID 30108208, 2018). "In addition, postmortem studies showed reduced GABRB3 expression in patients with autism." (PMID 24999380, 2014). "Cases I and II, are carriers of the same duplication on chromosome 15 [15q11.2q13.1(SNRPN,UBE3A,ATP10A,GABRB3,OCA2) x3], both have severe autism but with different levels of cognition." (PMID 28174603, 2017). "A significant positive correlation in GABRB3 and UBE3A transcript levels was observed with increased chromosomal copies when all cases (control, autism and dup15q) were analyzed as a group." (PMID 22152151, 2011). "A recent study reported widely decreased expression of genes encoding different subunits of GABA-AR, including GABRA1, GABRA2, GABRA3, GABRB3, GABBR1, and GABBR2, which is consistent with an earlier study reporting reduced GABRA1, GABRA5, and GABRB2 levels in the cortex of VPA-induced autism models." (PMID 35198562, 2021). "A cluster of three receptor subunit genes for the neurotransmitter GABAA (GABRB3, GABRA5, GABRG3) are biallelically expressed in control brain tissue samples, but show epigenetic alterations that result in monoallelic expression in a subset of autism cortical samples." (PMID 22152151, 2011). "Moreover, knockout mice lacking the GABRB3 gene display seizures, hypersensitive behavior, learning and memory deficits, and poor motor skills as features common to the Angelman syndrome, a disorder with some similarities to autism." (PMID 24400970, 2014).
autism (continued). "In contrast to both UBE3A and GABRB3, SNRPN levels were significantly negatively correlated with percentage PWS-IC methylation in all cases but not with dup15q, control or autism cases analyzed separately." (PMID 22152151, 2011).
Angelman syndrome (20 papers, 2004 to 2025). A neurogenetic disorder characterized by severe intellectual deficit and distinct facial dysmorphic features. "Instead, GABRB3 gene is well known to be associated with complex neurologic disorders including Rett syndrome (RS), Angelman syndrome (AS), ASD, and various types of epileptic disorders, including the EEs." (PMID 32945607, 2020). "Previous studies had reported that GABRB3 was associated with several neuropsychiatric disorders, such as such as Angelman syndrome, Prader-Willi syndrome, autism spectrum disorders, schizophrenia, and alcoholism." (PMID 25025424, 2014). "Deletions of the 15q11-13 region in humans—including GABRB3—are associated with Angelman syndrome and severe cognitive deficits, a constellation of phenotypes matched in Gabrb3-deficient mice." (PMID 22506031, 2012). "It is of interest that mice with mutations in the β-3 GABA receptor (GABRB3) at the Angelman syndrome (OMIM:105830) locus, also display cleft palate, implying a key role for GABA signalling in normal palate development." (PMID 15571623, 2004). "In the case of patient E7, a 43-year-old man and the eldest in the cohort, the presence of a deletion affecting the entire UBE3A and GABRB3 genes led to the suspicion of Angelman syndrome." (PMID 38328757, 2023). "Impaired motor learning was reported in several ASD mouse models such as GABRB3, Ube3a (Angelman's syndrome) and NF1 (Neurofibromatosis type 1) mice." (PMID 26973485, 2016). "Furthermore, significant GABRB3 reduction was observed in Rett syndrome and Angelman syndrome as well." (PMID 31590400, 2019). "GABRB3 and UBE3A are well-characterized candidate genes for ASD because they are associated with normal brain development and have been shown to be reduced in idiopathic autism, Angelman syndrome and Rett syndrome." (PMID 22152151, 2011). "In Angelman syndrome, a disorder highly penetrant for ID, beta power is reduced in cases caused by 15q11-q13 deletion relative to cases with etiologies that mainly impact UBE3A, suggesting a positive relationship between beta power and GABRB3/GABRA5/GABRG3 copy number." (PMID 31312421, 2019). "Angelman syndrome involves chromosome 15 deletions, particularly the q11–13 region, comprising the GABAA receptor beta 3 subunit (GABRB3) and ubiquitin ligase (UBE3A) genes." (PMID 33519379, 2020).
epileptic encephalopathies (17 papers, 2016 to 2025). "Genetic variants associated with developmental and epileptic encephalopathies have been identified in the GABRB3 gene that encodes the β3 subunit of GABAA receptors." (PMID 37647766, 2024). "Mutations in GABRB2 and GABRB3 genes have been associated with certain forms of epileptic encephalopathies, such as Dravet syndrome, Ohtahara syndrome, and West syndrome." (PMID 38136660, 2023). "Gain- and loss-of-function GABRB3 variants have been reported to correlate with distinct clinical phenotypes in individuals with developmental and epileptic encephalopathies." (PMID 38136660, 2023). "Overall, patients with GABRB3 variants that increase GABAergic activity have more severe developmental and epileptic encephalopathies." (PMID 35383156, 2022). "In particular, the Epi 4K consortium has identified four de novo mutations in the GABRB3 in children with epileptic encephalopathies." (PMID 33535681, 2021). "A literature review of clinical cases with various types of epileptic encephalopathies (EEs) related to GABRB3 mutations is reported." (PMID 32945607, 2020). "A literature review of cases with various types of epileptic encephalopathy related to GABRB3 mutations is discussed." (PMID 32945607, 2020). "Here we show functional analyses and structural simulations for three de novo missense mutations in the GABAA receptor β3 subunit gene (GABRB3) identified in patients with early-onset epileptic encephalopathy (EOEE) and profound developmental delay." (PMID 29162865, 2017). "Using a SureSelectXT custom multiple gene panel covering 48 early infantile epileptic encephalopathy/developmental delay genes, a novel de novo GABRB3 heterozygous missense mutation, c.860C>T (p.Thr287Ile), was identified and confirmed on Sanger sequencing." (PMID 26645412, 2016). "We report a novel mutation in GABRB3 in a patient with severe intractable early infantile epileptic encephalopathy." (PMID 26645412, 2016). "Similarly, the SST_PENK subtype exhibited significant alterations in GABA receptor complex signaling pathways, particularly through the upregulation of GABRB3, a gene associated with severe developmental and epileptic encephalopathies." (PMID 40313715, 2025). "In addition, the GABAAR coupling junction and pore GABRB3 mutations are linked to early-onset epileptic encephalopathy." (PMID 33535681, 2021). "They concluded that their results implicated the GABRB3 gene in epileptic encephalopathy." (PMID 33287870, 2020). "Encephalopathy is characteristic of 112 IMDs (19%) that are often classified as developmental and epileptic encephalopathies (DEE) (e.g., early infantile epileptic encephalopathies due to GABRA1, GABRB1, GABRB2 or GABRB3 pathogenic variants)." (PMID 35328062, 2022). "The phenotypic spectrum observed for GABRG2 variants, ranging from febrile seizures to epileptic encephalopathy, is similar to those of the other GABAA receptor genes GABRA1, GABRB2, and GABRB3." (PMID 35359574, 2022). "We report the clinical and electrographic features of a novel case of GABRB3‐related early‐onset epileptic encephalopathy." (PMID 26645412, 2016). "To date, five other cases of GABRB3 early infantile epileptic encephalopathy have been reported, to our knowledge." (PMID 26645412, 2016).
Anxiety (11 papers, 2012 to 2025). Intense feelings of nervousness, tension, or panic often arise in response to interpersonal stresses. "ASD mice models with FMR1, PTEN, UBE3A, and GABRB3 mutations exhibit learning deficits, stereotypic behaviors, and anxiety phenotypes." (PMID 33519379, 2020). "We find that anxiety-associated phenotypes are associated with variants near Gabrb3 (LRS>12, B allele) on Chr 7 (GeneNetwork BXD Trait IDs: 11389, 11390, 11385, 11388)." (PMID 22506031, 2012). "The single exception is Gabrb3, a locus that is linked to anxiety." (PMID 22506031, 2012). "Scn1a mutants, Gabrb3+/N328D knock-in mice, and young Scn2a mutant mice were also revealed to exhibit normal anxiety levels in several paradigms." (PMID 41585885, 2025). "Many genes, such as ADORA2A, NPY, DRD2, GABRB3, has shown relation with panic disorder in few studies, with supporting evidence of each gene having relation with panic disorder or, in part, anxiety related function." (PMID 31435520, 2018). "By contrast, sensory neuron, but not spinal cord neuron, loss of Gabrb3 expression promoted aberrant tactile, anxiety-like and social behaviors, consistent with a specialized role for this gene in peripheral sensory neurons." (PMID 38233682, 2024). "Anxiety is a trigger for seizures in some patients, and we thus wanted to assess whether there was significant anxiety-like behavior in the Gabrb3+/N328D mouse model by using the elevated zero maze." (PMID 37176165, 2023). "However, Gabrb3+/N328D did not display anxiety or deficient sociability that are characteristic of ASD, a comorbidity in a significant fraction of LGS patients." (PMID 37176165, 2023). "For example, the GABRB3 D120N knock-in mouse model was reported as the first genetic model for Lennox-Gastaut Syndrom, a severe form of childhood epilepsy, in 2020, and the knockin mice displayed spontaneous seizures, impaired learning and memory, and increased anxiety." (PMID 35477478, 2022). "Mouse models of GABRB3 and UBE3A deletions exhibit ASD phenotype including developmental delay, hyperactivity, epilepsy, impaired motor function, learning deficits, and anxiety-related behaviors." (PMID 33519379, 2020). "For example, Gabrb3+/N328D mutants showed reduced locomotor activity, impaired social interaction and anxiety symptoms, whereas Gabrb3+/D120N mutants did not, suggesting that motor deficits may secondarily influence behavioral outcomes." (PMID 41585885, 2025). "Moreover, Gabrb3+/D120N mice display impaired social interaction and anxiety, while Gabrb3+/N328D mice displayed no anxious behavior and normal sociability." (PMID 37176165, 2023).
Anxiety (continued). "For example, the human GABRA5 and GABRB3 are located in the 15q11.2-q13 region, and maternal duplications of 15q11.2-q13 leads to neurodevelopmental disorders including ASD, and their clinical symptoms often include anxiety, emotional lability, tantrums, and hyperactivity." (PMID 29391390, 2018).
autism spectrum disorder (10 papers, 2011 to 2023). A spectrum of developmental disorders that includes autism, and Asperger syndrome. "GABRB3 is a position candidate gene at chromosome 15q12 that has been implicated in the neurobiology of autism spectrum disorders (ASD)." (PMID 24999380, 2014). "GABAA receptor subunit genes GABRB3, GABRA5, and GABRG3 located on chromosome 15q11-q13 have been implicated in the etiology of autistic spectrum disorders (ASD)." (PMID 28607477, 2017). "Interestingly, GABRB3 is biallelically expressed in normal brain, including in newborns, but is imprinted in some cases of autistic spectrum disorders." (PMID 21545704, 2011).
epilepsy syndrome (7 papers, 2016 to 2026). A syndrome that has a characteristic cluster of clinical features and/or lectroencephalographic (EEG) findings that reflect underlying epileptic activity. "For instance, a recent study demonstrated that both gain-of-function and loss-of-function variants in GABRB3 are associated with epilepsy syndromes." (PMID 37176165, 2023). "Our report highlights the recent finding that mutations in GABRB3 are an emerging cause of early‐onset epilepsy syndromes." (PMID 26645412, 2016). "Intriguingly, early-onset DEEs were frequently observed for both individuals with GABRB2 and GABRB3 GOF, but while the peculiar epilepsy syndrome EIMFS was more prevalent in the GABRB3 GOF sub-cohort, EIDEE with a burst suppression pattern occurred at a higher frequency in the GABRB2 GOF group." (PMID 38996765, 2024).
Rett syndrome (7 papers, 2008 to 2024). A severe neurodevelopmental disorder affecting the central nervous system. "The EEG patterns characteristic for Angelman and Rett syndrome patients, respectively, also support the role of GABRB3 in the formation of epileptic phenotype." (PMID 31590400, 2019).
Intellectual disability (6 papers, 2016 to 2024). "The present data from Gabrb3 m-/p+ mice provide further support for the general principle of modulation of mGluRs affecting phenotypes associated with ASD and intellectual disability, while raising the possibility of differential effects in males and females." (PMID 27077953, 2016). "The paralogous GABRB3 LOF variant Y302C has been reported in four individuals with either focal epilepsy or intractable DEEs including IESS and mild to severe intellectual disability, yet none of these individuals were reported to have reflex seizures, and only one out of four were fever sensitive." (PMID 38996765, 2024).
Prader-Willi syndrome (6 papers, 2014 to 2025). "GABRB3 is associated with the pathogenesis of several disorders including Prader-Willi syndrome, the most common genetic cause of morbid obesity in children." (PMID 35500004, 2022). "For example, chromosomal region 15q11.2-q13.1, the critical region in 15q11-13 duplication syndrome and in Angelman and Prader-Willi syndromes contains three GABA receptor genes (GABRB3, GABRA5, and GABRG3)." (PMID 40490701, 2025). "Reduced GABRB3 expression has also been demonstrated in post-mortem Prader-Willi syndrome samples relative to controls." (PMID 40490701, 2025). "In the future, we will examine Prader Willi syndrome to further disentangling the electrophysiological roles of UBE3A and GABRB3/GABRA5/GABRG3." (PMID 31312421, 2019).